TNF (tumor necrosis factor)
Diseases named in the same sentence as TNF in open-access papers (continued):
Sharing a sentence is not in itself a finding about the gene and the disease.
eosinophilia (50 papers, 2006 to 2026). "Taken together, our results demonstrate a beneficial effect of combined anti-TNF/IL-6 administration including reduced Th2-associated eosinophilia and Th17/Th1-mediated neutrophilic infiltrate in the airways." (PMID 35408882, 2022). "Of these, IL‐5 and IL‐13 are hallmark cytokines of type 2 inflammation, involved in eosinophilia, smooth muscle cell contraction and mucus secretion, and TNF is important in several inflammatory diseases." (PMID 34873877, 2022). "Rather, a combination of both TNFα and IL-17A are required to get maximal neutrophil recruitment, whereas the production of IL-17A alone was associated with a more pronounced eosinophilia." (PMID 21936897, 2011). "In addition, we were interested in validating in this cohort the known associations of S. mansoni with circulating IL-10, TNF and eosinophilia." (PMID 30453907, 2018). "The cytokines such as IL-4, IL-5, and IL-13 are released causing eosinophilia and the pro-inflammatory cytokines like IFN-γ, TNF, IL-6, and IL-15 are increased promoting systemic inflammation." (PMID 41229508, 2025). "Damaged cells release interleukins such as IL−6, IL-1β, nitric oxide (NO•), prostaglandin E2 (PGE2), and tumor necrosis factor α (TNFα); the principal marker in these patients is the sputum eosinophilia." (PMID 36614301, 2023). "The activation of T lymphocyte and eosinophilia with increased peripheral proinflammatory cytokines IL-1β, IL-6 and TNF-α are identified as the main features of FD." (PMID 36091013, 2022). "Oral administration of 100 mg/kg extract caused 86% inhibition of eosinophilia, reduction of TH2 cytokines (IL-4, IL-5, IL-13) and TNF-α level in BALF and decreased serum IgE level in ovalbumin-sensitized mice." (PMID 31275149, 2019). "In contrast, the relative abundance of Moraxella and Streptococcus correlated positively with systemic and lower airway eosinophilia and bronchial pro-inflammatory cytokines including TNF and IL-7, respectively." (PMID 29885665, 2018). "There was a positive correlations between sputum HMGB1 expressions in sputum eosinophilia and sputum TNF-a, IL-5 and IL-13 levels." (PMID 28630596, 2017). "It has been proved that Toxocara canis invasion promotes release of IL-5, IL-8, and TNF-α, which is accompanied by eosinophilia with an inflammatory state." (PMID 19478959, 2009). "Neonatal RSV infection followed by adult exposure to allergen resulted in significantly higher lung resistance, along with increased total cellularity, eosinophilia, and increased TNF-α and Th2 cytokines (IL-5 and IL-13) in BALF." (PMID 16893457, 2006). "w., 5 days) relieved ovalbumin-induced airway inflammation, as evidenced by the reduction of eosinophilia, cytokines (IL-4, IL-5), tumor necrosis factor-α (TNF-α), immunoglobulin E (Ig E) and mucus production by increasing the expression of heme oxygenase-1 (HO-1)." (PMID 35847034, 2022). "In the asthmatic EMTU, the epithelial release of inflammatory cytokines (CCL-5, IL-1α, TNF-α, IL-8, and IL-6) can regulate mesenchymal inflammation to cause eosinophilia and TH2 inflammation (TSLP, GM-CSF) as well as neutrophilic inflammation (TNF-α, IL-8, IL-6)." (PMID 32679790, 2020). "Augmented TNF-α responses have been shown in the presence of eosinophilia." (PMID 29357863, 2018). "Eosinophil counts correlated with levels of both cytokines (r = 0.53, p = 0.001 and r = 0.38, p = 0.019, for IL-10 and TNF, respectively); the association of eosinophilia with schistosomiasis was not significant (OR = 2.538, p = 0.282)." (PMID 30453907, 2018). "Several previous cases of eosinophilia have been noted with TNF-α inhibitors." (PMID 27293946, 2016). "Progesterone, on the other hand, significantly increases the expression of IL-10, IL1-β, and TNF-α in the lungs, and augments the release of IL-4 by bone marrow cells, which may lead to eosinophilia." (PMID 21639909, 2011).
eosinophilia (continued). "The mechanisms behind the pulmonary manifestations may be similar, and due to the occurrence of eosinophilia and pulmonary infiltrations, suggest the role for cytokines such as tumor necrosis factor alpha (TNF-α), interleukin-5 (IL-5) and chemokines." (PMID 16756657, 2006). "CRSwNP-dominant regulators are engaged in T2 inflammation or eosinophilia, such as ERBB, TNF pathway, inflammatory and host defense, cytokine regulators and their cytokines, such as CSF2 or IL4, and angiogenetic factors." (PMID 36982612, 2023). "Thereby the combination of elevated non-TLR4 driven TNF-α and TLR-4 driven eosinophilia observed in AMP-LPS treated mice suggest AMP-LPS is a stronger stimulus for allergic inflammation in the airways than LPS alone." (PMID 29357863, 2018). "Combined IL-6/TNF inhibition, but not individual blockade of these two cytokines, led to complex anti-inflammatory effects including reduced Th2-induced eosinophilia and less prominent Th17/Th1-mediated neutrophilic infiltrate in the airways." (PMID 35408882, 2022). "A lower eosinophilia was detected in LPS-pretreated mice, along with an increase in phagocytes and regulatory cells (CD4+CD25+FOXP3+ and CD4+IL-10+), together with higher levels of IL-12 and TNFα." (PMID 32379832, 2020). "Augmented TLR4 driven eosinophilia and greater TNF-α responses observed in AMP-LPS treated mice independent of TLR-4 expression, suggests activation of allergic responses by TLR4 and non-TLR4 pathways larger than those induced by LPS administered alone." (PMID 29357863, 2018). "Although more and more of the previously identified risk factors can be linked with the other phenotypes, ARAD (neutrophilia, IL-1β, IL-8, IL-6, and TNF-α, CRP) and RAS (eosinophilia, CRP), protein profiles observed in this and previous reports 27 do not show significant changes." (PMID 24750386, 2014). "Taken together, we speculate that inhibition of NF-κB activation directly or indirectly attenuated IL-5, IL-13, eotaxin, RANTES, TNF-α, and TGF-β gene expression, eosinophilia infiltration, mucus production, collagen deposition, and allergic lung inflammation." (PMID 22675381, 2012). "The intermediate levels of IL-5 and TNF-α observed in RA subjects suggest that in some individuals elevated local concentrations of these cytokines remain, although in the absence of substantial eosinophilia." (PMID 23043798, 2012). "Our observations of increased Th1 (TNFα) and Th2 (IL-5, IL-33) cytokine concentrations in the BALF of dams fed a high fat diet, without any neutrophilia or eosinophilia suggest that these mice are ‘poised’ to react to further allergenic or viral exposure." (PMID 30700289, 2019).
intervertebral disc degeneration (50 papers, 2015 to 2026). "Intervertebral disc degeneration is mainly caused by irregular matrix metabolism in nucleus pulposus cells and involves inflammatory factors such as TNF-α." (PMID 37222533, 2023). "Activation of the proinflammatory-associated cytokine, tumor necrosis factor-α (TNF-α), in nucleus pulposus (NP) cells is essential for the pathogenesis of intervertebral disc degeneration (IDD)." (PMID 35265264, 2022). "Furthermore, higher levels of cytokines like TNF, IL-6 and IL-8 are linked to painful degenerative disk disease and can cause the infiltration of host immune cells as well as increased sensitization of nerve fibers upon AF and cartilage endplate ruptures." (PMID 39192354, 2024). "TNF-α is a potent pro-inflammatory cytokine that was closely associated with intervertebral disk degeneration, though it may also induce a downstream cascade of other cytokines involved in CLBP such as interleukin-6 or interleukin-1β." (PMID 35492573, 2022). "Both TNF-α and IL-6 are well-established pro-inflammatory cytokines known to take part in the pathology of intervertebral disc degeneration." (PMID 40095903, 2025). "As main frontier cytokines, nitric oxide (NO), interleukin (IL)‐1, interleukin (IL)‐6, and tumor necrosis factor alpha (TNF‐α) play key roles in the occurrence and progression of intervertebral disc degeneration and discogenic low back pain." (PMID 38097400, 2024). "IL-1β and TNF-α are mainly produced and secreted by immune cells, the expression of which is positively correlated with age and degree of intervertebral disk degeneration, and consistent with our study results." (PMID 37679790, 2023). "TNF-α, mainly by activating the NF-κB pathway, is related to various pathological processes of intervertebral disc degeneration." (PMID 38019477, 2023). "Patients were divided into the low- and high-score groups by the cumulative grade of intervertebral disc degeneration, and the cut-off value was 18 according to the levels of IL-6 and TNF-α." (PMID 35096205, 2022). "TNF-α is a kind of pleiotropic proinflammatory cytokines, deeply involved in a variety of pathological processes of intervertebral disc degeneration, including inflammatory responses and apoptosis." (PMID 35096205, 2022). "Animal studies have also reported an increased expression of TNF-α in multiple tissues during early chronic stages of intervertebral disk degeneration." (PMID 35492573, 2022). "SDC4 has an important effect on intervertebral disc degeneration induced by inflammatory factors, such as TNF-α and IL-1β." (PMID 36506585, 2022). "Intervertebral disc degeneration is related to varieties of proinflammatory cytokines IL-1 β, IL-6, and TNF-α and their metabolites." (PMID 34676010, 2021). "Inflammatory cytokines, particularly interleukin-1β and tumor necrosis factor (TNF)-α, accelerate the progression of intervertebral disc degeneration by upregulating matrix catabolic enzymes." (PMID 33218127, 2020). "Tumor necrosis factor-α (TNF-α) plays an important role in the process of intervertebral disc degeneration, and it also be the key reason for the low back pain." (PMID 29312639, 2017). "Mechanism study indicated Atsttrin protected against intervertebral disc degeneration by inhibiting TNF-α-induced inflammation." (PMID 29312639, 2017). "Different concentrations of GA were added to TNF-α-induced human nucleus pulposus cells (hNPCs) and intervertebral disc degeneration rat model." (PMID 28512264, 2017). "It’s widely accepted that TNF-α plays a critical role in the intervertebral disc degeneration process." (PMID 29312639, 2017). "ADAMTS-4 expression increased both in the TNF-α-induced nucleus pulposus cells and intervertebral disc degeneration rat model." (PMID 28512264, 2017). "Furthermore, dual-targeting EVTPD effectively degraded both TNF-α and IL-1β and exhibited potent anti-inflammatory effects in rat and goat models of intervertebral disc degeneration." (PMID 41526766, 2026).
intervertebral disc degeneration (continued). "TNF-α and IL-1β are the important inflammatory factors for intervertebral disc degeneration, which can induce intervertebral disc degeneration by reducing the anabolism of extracellular matrix proteins (Chen;Hodges;James and Diwan, 2021; Kim;Hong;Lee;Jeon and Ha, 2021)." (PMID 35837544, 2022). "During intervertebral disc degeneration, increased expression of TNF-α was observed." (PMID 34366712, 2021). "Intervertebral disk degeneration (IVDD) is a spinal disk condition caused by an inflammatory response induced by various proinflammatory cytokines, such as interleukin (IL)-1β and tumor necrosis factor (TNF)-α." (PMID 33015073, 2020). "Animal models of caudal vertebra intervertebral disc degeneration further demonstrated that apoptosis was induced by up-regulation of tumor necrosis factor (TNF) accompanied by down-regulation of NF-κB and MAPKs cascades that are dependent on caspase and RIPK1." (PMID 31029152, 2019). "Furthermore, TNF-α can also participate in the metabolism of nucleus pulposus cells, lead to the decomposition of extracellular matrix, and play an important role in intervertebral disc degeneration and herniation." (PMID 30008976, 2018). "Previous studies indicated that TNF-α could accelerate intervertebral disc degeneration, promote adjacent bone absorb and enhance endplate degeneration." (PMID 29312639, 2017). "During intervertebral disc degeneration, inflammatory factors such as IL-1β and TNF-α stimulate the nucleus pulposus cells to activate IκB kinase, thereby degrading IκB protein after ubiquitination and phosphorylation and exposing the NF-κB dimers, particularly dimer p65–p50." (PMID 28512264, 2017). "Through macro-genetic analysis of intestinal flora, our group found that DHJSD may regulate TNF, NF-kappa B, PI3K-Akt, MAPK signaling pathways through key proteins such as CASP8, TNF-α and IL-3 to slow down the apoptosis of NPCs and thus treat intervertebral disc degeneration." (PMID 37322524, 2023). "It has been shown that TNF-α might be a driver of intervertebral disc degeneration." (PMID 35096205, 2022). "Thus, our improved in vitro intervertebral disc degeneration model established with IL‐1β and TNF‐α intervention could be used in the further research for intervertebral disc degeneration." (PMID 32583517, 2020). "Likewise, a recent study showed that IL-21 played a role in the pathological development of intervertebral disc degeneration and it may worsen intervertebral disc degeneration by inducing TNF-α." (PMID 33014656, 2020). "Inflammatory cytokines, including interleukin-1 (IL-1), IL-6, and tumor necrosis factor-α (TNF-α), influence the development, progression, and severity of intervertebral disc degeneration (IVDD) and OP." (PMID 38745961, 2024). "They suggest that when intervertebral disc degeneration occurs, PLA2 is activated by various proinflammatory mediators, such as interleukin-1, tumor necrosis factor-α, and interleukin-6, which are secreted by the degenerative intervertebral disc." (PMID 36498718, 2022). "Intervertebral disc degeneration (IDD) is featured as enhanced catabolism of extracellular matrix (ECM) in the nucleus pulposus (NP), in which tumor necrosis factor-alpha (TNF-α)-related cell senescence is involved." (PMID 35880565, 2022). "So we conclude that TNF‐α and FSTL1 engage in a positive feedback loop to promote intervertebral disc degeneration." (PMID 34190406, 2021). "Previous studies have shown that intervertebral disc degeneration is a complex process of multi-factor interaction, in which a variety of cytokines are involved in the pathological progression of IVDD, e.g. IL-1β, TNF-α, IL-6." (PMID 34483910, 2021). "One postulated mechanism is that when intervertebral disk degeneration occurs, PLA2 is activated by various proinflammatory mediators such as interleukin-1, tumor necrosis factor-α, and interleukin-6, which are secreted by the degenerative intervertebral disk." (PMID 25879590, 2015).
intervertebral disc degeneration (continued). "And in this study, we observed inconsistent trends in IL-6 and TNF-α after surgery, which may indicate that TNF-α plays a more critical role in intervertebral disc degeneration." (PMID 35096205, 2022). "The analysis revealed through macrogenetic research of intestinal flora that DHJSD may modulate TNF, NF-kappa B, PI3K-Akt, MAPK signaling pathways through CASP8, TNF-α, IL-3, and other crucial proteins to inhibit apoptosis in the nucleus pulposus and treat rat intervertebral disc degeneration." (PMID 39418241, 2024).
candidiasis (49 papers, 2009 to 2025). Infection with the organism Candida. "We measured the expression of two key proinflammatory cytokines (interleukin-1 beta and tumor necrosis factor alpha) and the zebrafish IL-8 homolog, each of which is associated with response to Candida infection." (PMID 40172223, 2025). "In the presence of candidiasis, cytokines cause T cells to differentiate into Th1 cells under the action of IL-12 and TNF." (PMID 37545607, 2023). "The role of TNF-α in the development of protective Th1 immune response has been demonstrated against Candida infection, and depletion of TNF-α by etanercept treatment rendered mice more susceptible to disseminated C. tropicalis infection compared to controls." (PMID 34696267, 2021). "An increased risk of overall infections including herpes zoster and Candida infections is the only major concern associated with TNF-α and IL-17 inhibitors, respectively." (PMID 29144382, 2017). "IL-17RE-deficient and WT mice also exhibited similar induction of TNFα after infection, a cytokine known to be important in mediating immunity to systemic candidiasis." (PMID 25849644, 2015). "Candida infections and injection site reactions were more frequent with IL-7 inhibitors, whereas infusion reactions and serious infections were more commonly associated with TNF-α inhibitors." (PMID 41235248, 2025). "Macrophage-derived proinflammatory cytokines such as TNFα, IL-1, KC, or IL-6 activate the recruitment, phagocytosis, and killing of fungi, and mice deficient in these cytokines are more susceptible to systemic candidiasis (Basu and others 2008; Gorjestani and others 2012)." (PMID 27046240, 2016). "Smokers are seven times more likely to have oral Candida infections, partly due to reduced IL-1β, IL-6, and TNF-α responses and nicotine’s enhancement of CA biofilm formation and adhesion." (PMID 41009855, 2025). "Other cytokines such as TNF-α, IL-6, and GM-CSF are also involved in neutrophil recruitment during candidiasis." (PMID 38787374, 2024). "The higher levels of specific TNFα/IFNγ-producing cells suggest a robust Th1 immune response, which is beneficial for controlling invasive Candida infections." (PMID 38904363, 2024). "Th1 response is characterized by the production of proinflammatory cytokines IFN-γ and TNF-α and offers a protective immune response to the host against Candida infections." (PMID 39062060, 2024). "Monocyte-deficient mice are more susceptible to C. albicans infections, and monocytes exposed to C. albicans release tumor necrosis factor-α (TNF-α), which protects the host from invasive candidiasis." (PMID 38404288, 2024). "Studies have shown that N. (Candida)glabrata and C. albicans infection induce the specific proinflammatory cytokines TNF-a, IL-12, and IFN-g, being TNF-a the major one in host defense against systemic candidiasis cases." (PMID 36144457, 2022). "The duration of biological therapy in participants with candidiasis in the anti-TNF-α group was five years in one participant and six months in the other participant, whereas the duration of treatment in the anti-integrin-α4β7 group was four years." (PMID 35323234, 2022). "Monocyte deficient mice are more susceptible to infections with C. albicans, and monocytes exposed to C. albicans produce tumor necrosis factor-α (TNF-α), which is required for surviving systemic candidiasis." (PMID 34696267, 2021). "It has been reported that the earliest stages of Candida infection induces the local production of TNF-α." (PMID 27253525, 2016). "TNF-α was involved in the innate immune response against Candida infection through promotion of neutrophil production and activation." (PMID 27144456, 2016). "TNF-α and IL-6 participate in the innate immune response against Candida infection by promoting neutrophils production and activation." (PMID 27708385, 2016).